SLC7A11 (solute carrier family 7 member 11)
Diseases named in the same sentence as SLC7A11 in open-access papers (continued):
Sharing a sentence is not in itself a finding about the gene and the disease.
cancer (continued). "OTUB1, which is overexpressed in multiple human cancers, directly interacts with SLC7A11 to remove its ubiquitination marks, preventing proteasome-mediated degradation and increasing its stability, thus inhibiting the activation of ferroptosis." (PMID 39769177, 2024). "SLC7A11 expression is significantly upregulated in several types of cancers in which it can inhibit ferroptosis and favor cancer cell proliferation, invasion and chemoresistance." (PMID 38203758, 2024). "In preclinical studies, glucose transporter (GLUT) inhibitors have been shown to induce disulfidptosis in SLC7A11-overexpressing cancer cells, effectively suppressing tumor growth while minimizing toxicity to healthy tissues." (PMID 39687628, 2024). "SLC7A11 was found to render cancer cells more dependent on glucose and increase the sensitivity of cells to glucose starvation-induced cell death." (PMID 38705513, 2024). "For example, inhibitors of cystine-glutamate antiporter (xCT/SLC7A11) have gained attention for their potential in modulating oxidative stress in cancer and neurodegeneration." (PMID 38886311, 2024). "Overexpression of SLC7A11 promotes tumor growth by inhibiting ferroptosis, making it a potential therapeutic target for cancer treatment." (PMID 39195490, 2024). "The expression of SLC7A11 is frequently elevated in cancer cells and tissues, enabling cancer cells to increase intracellular GSH levels and counteract ferroptosis." (PMID 39624080, 2024). "Cancer cells with elevated levels of SLC7A11 expression exhibit an increased affinity for cystine, which they rapidly convert into cysteine." (PMID 39040097, 2024). "We identified IL-6 as a novel target of ERO1α and confirmed the suggestion by previous studies conducted using other cancer cell models that STAT3 directly transcriptional regulates SLC7A11." (PMID 38610018, 2024). "We underscore the credibility and reproducibility of the observed metabolic shifts in cancer cells with varying SLC7A11 expression levels." (PMID 39040097, 2024). "Extensive evidence has indicated that SLC7A11 overexpression within cancer cells propagates disulfide-induced cell death post-glucose deprivation." (PMID 38531930, 2024). "The overexpression of SLC7A11 is commonly observed in many types of cancer, and SLC7A11 has been established as a key inhibitor of ferroptotic signaling." (PMID 39573995, 2024). "Stem cell transcription factor SOX2 endows cancer cells with resistance to ferroptosis by activating SLC7A11." (PMID 38739940, 2024). "The expression of SLC7A11 is observed in various tissues and it serves multiple functional roles in the pathophysiology of different diseases, such as cancer." (PMID 38686047, 2024). "Research has demonstrated that the SLC7A11 molecule is critical for the development, spread, metastasis, and resistance to several drugs for various types of cancers." (PMID 38994627, 2024). "As a member of the glutamate/cystine reverse transport system (system Xc-), SLC7A11 suppresses the development/progression of several cancers." (PMID 39170701, 2024). "Conversely, high expression of SLC7A11 protects cancer cells from oxidative stress and iron toxicity by promoting cystine uptake and synthesis of reduced GSH." (PMID 39029955, 2024). "The hypermethylated genes SLC7A11 and CD2AP were primarily associated with better prognosis in cancer, whereas the hypomethylated gene MYL6 was predominantly associated with poor prognosis in PCPG." (PMID 38862242, 2024).
cancer (continued). "It has been reported that miR-490-3p and SLC7A11 are promising molecular markers for early cancer diagnosis and prognosis." (PMID 39029955, 2024). "A number of compounds, such as erastin, sulfasalazine, and sorafenib, act as SLC7A11 inhibitors and have been found to induce ferroptosis, leading to cancer cell death." (PMID 39335604, 2024). "SLC7A11 is not only a potent target of ferroptosis but is also considered an adaptive resistance barrier molecule that promotes cancer therapy, and it also plays a crucial regulatory role in disulfidptosis." (PMID 38786003, 2024). "Sorafenib, a multi-kinase inhibitor used for advanced cancers, is thought to induce ferroptosis by targeting SLC7A11." (PMID 39624080, 2024). "Beyond its well-documented antioxidant functions, SLC7A11 emerges as a pivotal metabolic regulator that profoundly influences intracellular nutrient processing and energy metabolism within cancer cells." (PMID 39040097, 2024). "Recent literature highlights the importance of SLC7A11 in modulating ferroptosis resistance in cancer and its emerging potential as a target for combination therapies." (PMID 39944353, 2024). "SLC7A11, an amino acid transporter that facilitates cysteine uptake in exchange for glutamate, plays a crucial role in sustaining the altered metabolism of cancer cells." (PMID 38073087, 2024). "And then, to further determine the relationships among ZN706, MYC, and SLC7A11 in the protein level, we performed IHC analysis on cancer tissue chips to examine their expression pattern." (PMID 38862581, 2024). "SLC7A11 is involved in the uptake of sulfated amino acids by cells with increasing expression led to increased resistance to chemotherapy drugs in cancer." (PMID 38244584, 2024). "This leads to the collapse of the histone skeleton and cell death, indicating that SLC7A11-regulated disulfidptosis has the potential to be a new target for cancer therapy." (PMID 38817361, 2024). "This suggests that SLC7A11-high tumors are likely resistant to therapies that induce ferroptosis and apoptosis and that this vulnerability of cancer cells to disulfidptosis offers new therapeutic opportunities for treating SLC7A11-high cancers." (PMID 38584831, 2024). "Disulfidptosis primarily occurs in cancer cells with high expression of SLC7A11, which results from an inadequate supply of NADPH to support the reduction of cystine to cysteine, leading to disulfide stress." (PMID 38334964, 2024). "BEBT-908, which is a dual PI3K/HDAC inhibitor, triggers a robust ferroptotic response in cancer cells, characterized by the reduction of SLC7A11 and GPX4, heightened lipid ROS and MDA levels, and activation of ferroptotic signaling." (PMID 38562143, 2024). "Solute carrier family 7 member 11 (SLC7A11) is the transporter subunit in system xc that takes up cystine, and inhibiting SLC7A11 activity by FINs, such as erastin, induces ferroptosis in many cancer cells." (PMID 38378601, 2024). "Disulfidptosis is a new form of regulated cell death in cancers with high SLC7A11 expression under glucose starvation conditions, providing a novel therapeutic strategy for treating malignant tumors." (PMID 38840910, 2024). "OTU deubiquitinase B1(OTUB1), an atypical deubiquitinase prevalent in numerous human cancers, principally stabilizes SLC7A11 by impeding its ubiquitination and subsequent proteasomal degradation." (PMID 38515565, 2024). "SLC7A11-high cancer cells manifest heightened sensitivity to GLUT1 inhibitors compared to SLC7A11-low cancers." (PMID 38910181, 2024). "The study further demonstrated that carmustine enhanced the sensitivity of cancer cells to disulfidptosis by inhibiting the expression of SLC7A11, a key gene involved in disulfidptosis." (PMID 38817361, 2024). "The disulfidptosis genes: NCKAP1, LRPPRC, SLC7A11, OXSM, SLC3A2, NDUFS1, and GYS1 occurred somatic mutations in pan-cancer, with 1 % SNV frequency." (PMID 39605832, 2024).
cancer (continued). "It triggers ferroptosis in gastric cancer cells by manipulating the miR-489–3p/SLC7A11 pathway, thereby hindering cancer cell proliferation." (PMID 39040097, 2024). "The lack of cystine is crucial for inducing ferroptosis in cancer cells, and many cancers upregulate SLC7A11 to obtain a sufficient supply of cystine and avoid ferroptosis." (PMID 38180745, 2024). "Erastin, a classic ferroptosis inducer, directly binds and inhibits the activity of SLC7A11, thereby inducing ferroptosis in cancer cells." (PMID 39624080, 2024). "It was recently discovered to play an anti-cancer role in various cancers, including malignant glioma, by inhibiting SLC7A11-activated ferroptosis." (PMID 38304870, 2024). "For instance, in most cancer types, the expression of SLC7A11, OXSM, and NDUFS1 was negatively correlated with methylation." (PMID 38397869, 2024). "The results showed that Ferroptosis-related genes such as SLC3A2, HSF1, and SLC7A11 were significantly positively correlated with SPC25 in pan-cancer." (PMID 38605119, 2024). "On a clinicopathological level, SLC7A11 has been observed to be overexpressed in various types of cancer." (PMID 38603713, 2024). "This concept emerged from extensive studies on the function of the solute carrier family 7 member 11 (SLC7A11) in cancer cells." (PMID 39415848, 2024). "Together, our results suggest that SNF2L modulates SLC7A11 expression across multiple cancer cell types through gene transcription." (PMID 39532848, 2024). "Many studies revealed that the overexpression of SLC7A11 occurs in various types of malignancies, promotes the development and proliferation of them, and confers a survival advantage to cancer cells." (PMID 38671348, 2024). "Disulfidptosis is triggered when cancer cells with high SLC7A11 expression are subjected to glucose starvation, and disulfidptosis-related genes (DRGs) were identified via CRISPR–Cas9 screening." (PMID 38962013, 2024). "Several miRNAs, such as miR-1261, miR-143-3p, miR-34c-3p, miR-382-5p, and miR-489-3p, were reported to induce ferroptosis in cancer cells by targeting and downregulating the ferroptosis-inhibiting SLC7A11 gene." (PMID 38892270, 2024). "SLC7A11 is crucial for ferroptosis antagonism and has been shown to be highly expressed in cancers and reflective of a poor prognosis." (PMID 38395990, 2024). "Solute carrier family seven-member 11 (SLC7A11) has emerged as a promising biomarker and therapeutic target in cancer diagnosis and treatment." (PMID 38531930, 2024). "The SLC7A11-GSH-GPX4 signaling pathway has been reported as the primary anti-ferroptosis system in cancer cells." (PMID 38378601, 2024). "Among SLCs, a body of studies highlighted the critical function of SLC7A11 in cancer and revealed the underlying mechanisms, upstream and downstream factors, or pathways by which SLC7A11 plays its roles in cancer." (PMID 38705513, 2024). "Given the crucial role of GSH in regulating redox balance, certain molecules involved in GSH metabolism, such as GPX4 and SLC7A11, have been identified to impede ferroptosis in cancer cells." (PMID 39548421, 2024). "SLC7A11, a crucial component of the cystine/glutamate antiporter that blocks ferroptosis, is overexpressed in various human cancers, including liver cancer." (PMID 38540172, 2024). "Sorafenib/UA induced ferroptosis in various human cancer cells by decreasing the level of SLC7A11 and inciting dramatic accumulation of intracellular ROS." (PMID 39021832, 2024). "SLC7A11 acts as an oncogene against oxidative stress and ferroptosis and affects cancer phenotypes and the immune system." (PMID 38353724, 2024). "Disulfidptosis is a form of regulated cell death (RCD) reported in cancers characterized by a high expression of solute carrier family 7 member 11 (SLC7A11)." (PMID 38962013, 2024).
cancer (continued). "This study identified marine database SLC7A11 inhibitors as promising candidates for inducing ferroptosis in cancer cells." (PMID 39195490, 2024). "Cancer cells with high expressions of SLC7A11 are more sensitive to glutamine and glucose starvation, which accelerates metabolic processes." (PMID 38469234, 2024). "SLC7A11/xCT is highly expressed in a variety of tumors, and this correlates with the proliferation, invasion, metastasis, and drug resistance of cancer." (PMID 38790657, 2024). "Prior research established disulfidptosis as a predictive biomarker for immune characteristics and drug responses, suggesting SLC7A11-mediated disulfidptosis as a novel therapeutic strategy in cancer." (PMID 38397869, 2024). "Conversely, GBM was found to potentially have a lower disulfidoptosis cell death rate in cancer tissue because their pro-disulfidoptosis gene SLC7A11 is downregulated in cancer tissues." (PMID 38397869, 2024). "The shortage leads to the overexpression of the cystine transporter solute carrier family 7 member 11 (SLC7A11) in cancer cells, which induces abnormal accumulation of disulfide (such as Cystine, etc.)in cells, ultimately leading to cell death." (PMID 38862217, 2024). "For example, the overexpression of SLC7A11 in certain cancers can be targeted by sulfasalazine to induce ferroptosis, whereas lapatinib, despite its ferroptotic induction capability, does not directly target SLC7A11, potentially limiting its effectiveness." (PMID 38844964, 2024). "Disulfidptosis is defined as the accumulation of cystine by cancer cells with high expression of the solute carrier family 7 member 11 (SLC7A11) during glucose starvation." (PMID 38685115, 2024). "Disulfidptosis, which is a newly recognized form of regulated cell death in cancers with high SLC7A11 expression under glucose starvation conditions, is a novel therapeutic strategy for treating malignant tumors." (PMID 38962013, 2024). "A growing body of evidence indicates that SLC7A11/GPX4 signaling activity can promote the progression of cancer by limiting ferroptotic induction." (PMID 39573995, 2024). "For instance, 5-methylcytosine (m5C) and N6-methyladenosine (m6A) modifications have been identified to upregulate SLC7A11 mRNA in cancer cells, leading to ferroptosis resistance." (PMID 39624080, 2024). "In disulfidptosis, the depletion of NADPH increases cystine in SLC7A11-overexpressing cancer cells, which eventually leads to the accumulation of intracellular disulfide molecules and cell death." (PMID 38654314, 2024). "Cys for GSH synthesis is imported via the cystine/glutamate antiporter SLC7A11, which is overexpressed in human cancers." (PMID 38674143, 2024). "Currently, research on disulfidptosis is focused on cancer cell lines that overexpress SLC7A11 and are under glucose starvation." (PMID 38862217, 2024). "For example, cancer cells exhibit higher glucose uptake and resist apoptosis and ferroptosis by overexpressing SLC7A11, leading to chemotherapy resistance." (PMID 39415848, 2024). "Several FDA-approved anti-cancer drugs, including sorafenib, can induce ferroptosis by inhibiting SLC7A11 activity, even though they also elicit apoptosis in preclinical studies." (PMID 39090114, 2024). "SLC7A11, a key regulator of ferroptosis that is often overexpressed in many cancers, plays a crucial role in promoting GSH biosynthesis and ferroptosis resistance." (PMID 39657365, 2024).
cancer (continued). "We next searched the Cancer Genome Atlas (TCGA) database for altered expression of SLC7A11, KCTD10, and USP18 in human cancer tissues." (PMID 38959043, 2024). "Subsequent studies have shown that moderate overexpression of SLC7A11 benefits cancer cells treated with H2O2, a common oxidative stress inducer, by inhibiting oxidative stress‐induced apoptosis." (PMID 39415848, 2024). "CD8+ cytotoxic T cells, key players in antitumor immunity within the TME, release interferon-γ (IFNγ), which inhibits cystine uptake in cancer cells by downregulating SLC7A11 expression." (PMID 38322268, 2024). "The inhibition of SLC7A11 on the ferroptosis pathway has been assessed in a variety of cancers previously." (PMID 38383528, 2024). "Cancer cells usually acquire cysteine via the uptake of extracellular cystine, with solute carrier family 7 member 11 (SLC7A11), also known as xCT, serving as an important transporter of cystine." (PMID 38862581, 2024). "In this context, GLUT1 inhibitors, such as WZB117, represent a promising tool for potentially inducing disulfidptosis in cancer cells overexpressing SLC7A11, given their dependence on glucose uptake." (PMID 39687628, 2024). "Under glucose starvation conditions, high SLC7A11-expressing cancer cells experience depletion of the intracellular NADPH pool, resulting in the accumulation of intracellular cystine and other disulfides, leading to rapid cell death." (PMID 38831301, 2024). "Further analysis revealed that SLC7A11, which was highly expressed in cancer cells, mediated the uptake of cystine and consequently the synthesis of glutathione to counteract the oxidative effect caused by high expression." (PMID 38388539, 2024). "Ferroptosis was induced in many cancer cells when cystine was removed from cell culture or when SLC7A11 was inactivated by gene ablation or drug inhibition." (PMID 38730240, 2024). "In the following sections, we will introduce several common categories of ferroptosis inducers utilized in cancer treatment, including SLC7A11 and GPX4 inhibitors, as well as the repurposing of clinical drugs as ferroptosis inducers." (PMID 39624080, 2024). "The first involves the development of direct inhibitors targeting SLC7A11 to impede cystine uptake in cancer cells, thereby diminishing intracellular GSH levels and inducing cancer cell ferroptosis." (PMID 39040097, 2024). "SLC7A11 is a key determinant for cystine transport and ferroptosis, and is often dysregulated in many human diseases, including cancer." (PMID 38959043, 2024). "The promotion of antitumor immunity is facilitated by CD8+ T cells, which secrete interferon-γ (IFNγ), leading to the repression of SLC7A11 expression in cancer cells and subsequently inducing ferroptosis." (PMID 39544291, 2024). "The regulation of SLC7A11 is affected by multiple dimensions, and also abnormal regulation of SLC7A11 leads to malignant tumors related to proliferation, invasion, metastasis and drug resistance." (PMID 39040097, 2024). "Cancer cells import cystine from the extracellular environment via solute carrier family 7 member 11 (SLC7A11) and convert it to cysteine using nicotinamide adenine dinucleotide phosphate (NADPH)." (PMID 39415848, 2024). "As such, the increase in the expression and activity of SLC7A11 in cancer cells brings in cystine from circulation to promote glutathione synthesis, thus providing a mechanism for cancer cells to protect themselves from iron-induced cell death." (PMID 38339256, 2024). "Cancer cells often experience high levels of oxidative stress, necessitating cystine intake via SLC7A11 for the synthesis of glutathione (GSH), which can help to counteract oxidative damage." (PMID 38739940, 2024). "SLC7A11 is the most important protector of cancer cells from iron-induced ferroptosis because of its ability to increase cellular levels of glutathione." (PMID 38891084, 2024).